NR1D1 (nuclear receptor subfamily 1 group D member 1)
Diseases named in the same sentence as NR1D1 in open-access papers (continued):
Sharing a sentence is not in itself a finding about the gene and the disease.
cancer (continued). "It appeared in different cancer datasets, specifically in THB (P10828), VDR (P11473), NR1D1 (P20393), and RORA (P35398)." (PMID 40334012, 2025). "This discordance between NR1D1 and NR1D2 is a possible source of the small amplitudes in RRE-targets NPAS2, NFIL3, and CRY1 in the cancers." (PMID 40424435, 2025). "The low levels of NR1D1 and NR2E3 expression in RB are consistent with previous findings in other cancers." (PMID 38480634, 2024). "Synthetic NR1D1/2 agonists, such as SR9009 and SR9011, showed cell cytotoxicity in cancer cells derived from glioblastoma, leukemia, colon cancer, and melanoma." (PMID 37524704, 2023). "We generated CC manipulated CRC cells (ARNTL, PER2 or NR1D1 knockout or knockdown) and compared clock (ARNTL-promoter activity) and cancer phenotype (proliferation, apoptosis and invasion) to that of MACC1 manipulated (knockout or overexpression) cells." (PMID 35884519, 2022). "In cancer, several CC genes, including CLOCK, ARNTL, PER2 and NR1D1 are dysregulated and play a role in tumourigenesis." (PMID 35884519, 2022). "Compared with the adjacent normal tissues, the expression of NR1D1, DBP, and BHLHE40 was increased, while the expression of CRY1 and CLOCK was decreased in cancer tissues." (PMID 34977153, 2021). "Whereas there are nine rhythm genes (MTNR1B, NR1D1, RORB, RORA, OPN4, C1orf51, PROK2, SERPINE, and EGR3) that are differently expressed in the high and low MSI group in more than 1/3 cancer types." (PMID 31927791, 2020). "ARNTL2 was one of the most amplified genes found in 16 cancers, followed by RORC in 14 cancers and NR1D1 and CRY1 in 12 cancers each." (PMID 31014368, 2019). "Several of the direct FOXP1 targets upregulated in response to cancer were transcriptional repressors of the circadian clock, including Kfl9, Nr1d1, Per1, and Bhlhe40, providing further evidence that FOXP1 is a negative regulator of clock function in skeletal muscle in response to cancer." (PMID 40349340, 2025). "In our previous work, we investigated the role of circadian clock components in altering the expression of genes related to cancer hallmarks in CRC cell lines and pointed to a role for ARNTL and NR1D1 in regulating cancer growth and apoptosis, as well as metastasis potential." (PMID 35884519, 2022). "Primary or subgroup meta-analysis for the SNPs concerning all the other clock genes (ARNTL, CRY1, CSNK1E, NR1D1, TIMELESS) considered in this study were found to be not statistically significantly associated with cancer risk." (PMID 28177907, 2017). "With the exception of three clusters of NRs representing NR classes I (cluster I: RORC, VDR, PPARA, NR1D1, THRA, RORA, NR1H3; cluster II: RARB, PPARG, THRB) and III (cluster III: ESR1, PGR, AR, ESRRG), NR class was not a good determinate of NR expression patterns in the different cancer types." (PMID 32024906, 2020). "In order to achieve a systematic understanding of circadian clock in cancer, we define a core subset of clock family genes including 7 positive regulators (CLOCK, NPAS2, ARNTL, ARNTL2, RORA, RORB, and RORC) and 7 negative regulators (PER1, PER2, PER3, CRY1, CRY2, NR1D1, and NR1D2)." (PMID 31708917, 2019). "REV-ERBα is unique member of the nuclear receptor subfamily 1 group D member 1 (NR1D1) of proteins it has repressive functionin cell proliferation and metabolism, which may be relevant during cancer pathogenesis.BRMS1 metastasis suppressors may represent novel therapeutic targets for metastasis." (PMID 40230904, 2024). "The two datasets with the highest ΔCCD (>50% higher than any ΔCCD we observed in human cancer) were those in which the knockout mice lacked not one, but two components of the clock (Cry1 and Cry2 in GSE13093; Nr1d1 and Nr1d2 in GSE34018)." (PMID 29404219, 2018).
tumor (37 papers, 2011 to 2025). "Our study provides evidence for a potential tumor-suppressing function of NR1D1 in RB, based on the novel findings that low expression levels of NR1D1 associated with advanced disease stage and choroidal and optic nerve infiltration." (PMID 38480634, 2024). "One study reported that deletion of Nr1d1 in mouse models resulted in increased tumor growth and metastasis, primarily driven by Nr1d1 loss in tumor cells." (PMID 39185402, 2024). "Consistent with the findings obtained from tumor-bearing lung tissues, NR1D1 deficiency led to increased mRNA expression of Nlrp3, Il1β, and Il18 in AM, as well as increased protein expression of NLRP3 and cleaved caspase-1 in both AM and normal lung tissues." (PMID 37524704, 2023). "First, we investigated whether NLRP3 inflammasome was activated in the tumor-bearing lungs of NR1D1-deficient mice." (PMID 37524704, 2023). "Moreover, CS exposure decreased Nr1d1 expression in both tumor-resistant and tumor-susceptible mice, making them more prone to developing CS-related lung cancer." (PMID 38067152, 2023). "NR1D1 enhances anti-tumor immunity via activating cGAS-STING pathway and promoting CD8+ T-cell responses." (PMID 40567603, 2025). "In normal retina and non-tumor retina tissues, NR1D1 and NR2E3 were expressed in the cell nucleus of the outer nuclear layer, inner nuclear layer, and ganglion cell layer, especially high-expressed in the outer nuclear layer." (PMID 38480634, 2024). "Based on previous reports that the major factors of the circadian clock are closely related to tumorigenesis, NR1D1 is also expected to affect tumor development." (PMID 37524704, 2023). "Deletion or overexpression of NR1D1 in the tumor microenvironment increased or reduced lung tumor development in an NLRP3 inflammasome-dependent manner, suggesting that NR1D1 acts as a tumor suppressor in the lung tumor microenvironment." (PMID 37524704, 2023). "NR1D1 is now recognized as a tumor suppressor since it was shown to abrogate tumor cell proliferation, lipid metabolism, autophagy, and DNA damage response (DDR) in several cancer types." (PMID 34743206, 2022). "We also establish an inverse correlation between Ran and the tumor suppressor NR1D1 and reveal the critical role of Ran/NR1D1 axis in aneuploidy-associated endogenous DNA damage repair." (PMID 34743206, 2022). "Tumors with NR1D1 over-expression were smaller than the controls (vector), with lighter tumor weights." (PMID 34330232, 2021). "STAD patients with high pTNM stage and high tumor grade had low NR1D1 expression compared with that of patients with low pTNM and low tumor grade." (PMID 34162762, 2021). "Altogether, our results suggest an essential role for BMAL1 and NR1D1 in survival of HCT116 tumours and point to an NR1D1 specific role in metastatic potential in vivo." (PMID 32244760, 2020). "On the other hand, and similar to BMAL1 KD, the downregulation of NR1D1 led to a significant reduction of proliferation (~50% reduction, p = 0.0008) and tumour size (~24% reduction, p = 0.0012)." (PMID 32244760, 2020). "Administration of RIP‐12 inhibited the growth of IMR‐32 cell‐derived xenograft tumors, as evidenced by reduction in tumor volume, weight, and Ki‐67 proliferative activity, along with up‐regulation of NR1D1, RIOK3, FLCN, or FNIP1 as well as down‐regulation of LAMP1." (PMID 40899609, 2025). "In our study, NR1D1 and NR2E3, which play a critical role in the development and differentiation of photoreceptors, showed low expression levels in RB tumor tissues compared to retina and were strongly associated with invasive clinicopathological features of RB." (PMID 38480634, 2024). "Based on these analyses, we investigated whether NR1D1 plays a tumor suppressive role in lung tumorigenesis." (PMID 37524704, 2023). "We revealed that NR1D1 plays a tumor suppressive role in the TME during lung tumorigenesis." (PMID 37524704, 2023).
tumor (continued). "The differentiation-induced change in expression of eight of these genes was confirmed (i.e., comparison of freshly isolated M-MDSCs from spleen versus tumor); only the downregulation of Nr1d1 mRNA in tumor M-MDSCs was different from what we observed in the microarray experiment." (PMID 36480485, 2022). "Furthermore, NR1D1 has been shown to harbor tumor suppressor potential and as observed with Ran KD, its activation has been shown to display a differential sensitivity between normal and transformed cells." (PMID 34743206, 2022). "NR1D1 signals were found predominantly in the nuclei of tumor cells in almost all samples." (PMID 31779659, 2019). "Besides, its in vivo growth was also repressed by over-expression of NR1D1, indicating that NR1D1 may act as a tumor suppressor." (PMID 34330232, 2021). "The expression of NR1D1 and NR2E3 were found to be lower in RB tumor tissues than in normal and non-tumor retinal tissues." (PMID 38480634, 2024). "The expression levels of NR1D1 (P = 0.004) and NR2E3 (P = 0.024) were significantly lower in RB tumor tissues than in normal retina." (PMID 38480634, 2024). "The expression levels of CUL1, NR1D1, and PER2 were lower in tumor deletion samples than in other tumor and normal tissue samples." (PMID 36439444, 2022). "PPAR-Riskscore was constructed by univariate Cox regression based on the expression of 4 genes (NR1D1, ILK, TNFRSF1A, and REN) in tumor tissues." (PMID 35481240, 2022). "For example, NR1D1 significantly increase the number of macrophages, dendritic cells and CD8+ T cells infiltrating in tumor tissues through activation of the cGAS-STING signaling pathway, thereby enhancing the anti-tumor immune effect and inhibiting breast cancer lung metastasis." (PMID 40166469, 2025). "Additionally, further exploration of the biological mechanisms underlying RB progression is necessary, particularly to determine if NR1D1 and NR2E3 serve as early indicators of more aggressive RB or if these genes are downregulated as the tumor grows." (PMID 38480634, 2024). "In this research, we conveyed immunohistochemical (IHC) staining to examine the expression of NR1D1 and NR2E3 in the tumor tissues of RB patients, and explored their correlation with clinical and pathological features of RB, including disease stages, infiltration of the choroid and optic nerve." (PMID 38480634, 2024). "Tumors with NR1D1 over-expression showed increased TUNEL staining with distinct regions of apoptosis/necrosis unlike tumors in the control group, which was consistent with the decreased tumor volumes." (PMID 34330232, 2021).
metabolic disease (17 papers, 2018 to 2025). A congenital disorder (due to inherited enzyme abnormality) or acquired (due to failure of a metabolically important organ) disorder resulting from an abnormal metabolic process. "Furthermore, activating Nr1d1/2 with agonists has been demonstrated to result in anti-inflammatory effects, the regulation of metabolism, and improvements in inflammatory and metabolic diseases." (PMID 36077427, 2022).
infection (11 papers, 2015 to 2023). The state of being infected such as from the introduction of a foreign agent such as serum, vaccine, antigenic substance or organism. "Accordingly, the MS‐HRM analyses we used to verify the relationship between methylation proportion and infection status for NR1D1 and CLDN22 serve as a first step toward substantiating the results of the differential methylation analyses in this study." (PMID 36447599, 2022). "Infection efficiency was near 100%, and we found that the adenovirus induced Cre expression results in a 94% reduction of Nr1d1 and an 87% reduction of Nr1d2 in the ad-Cre-GFP infected CFs." (PMID 36386186, 2022). "The most active period of LPS-induced changes in SCN state seemed to occur about 8 hours after the infection; at this time, the Per2 was induced after the daytime LPS injection, compared to Nr1d1 after the night-time LPS injection." (PMID 30265676, 2018). "Thus, although published precedent supports NHR-42 as a functional homolog of NR1D1, the regulation of NHR-42/NR1D1 by HLH-30/TFEB during infection is a novel and important interaction that could be exploited for therapeutic purposes." (PMID 36860863, 2023). "Because methylation proportion at NR1D1 was positively related to S. trachea infection status, we investigated whether juvenile recruitment probability was related to methylation proportion at NR1D1 or to infection status." (PMID 36447599, 2022). "Deletion of Bmal1 in primary Bmal1fl/fl neuron cultures via infection with an AAV8-Cre viral vector (versus AAV8-eGFP control) suppressed the BMAL1 transcriptional target Nr1d1 (which encodes REV-ERBα) by 85% and induced C4b expression but caused no increase in C3." (PMID 33258449, 2020). "The daytime point of infection coincides with high levels of STAT3 protein and of clock genes Per1, Per2 and Nr1d1 mRNAs, and was chosen to deduce a possible LPS-induced decrease of their levels." (PMID 30265676, 2018). "Then, we used methylation‐sensitive high‐resolution melting to verify that methylation level at NR1D1, but not CLDN22, remained related to infection status in a larger sample dataset, and that juvenile recruitment probability was positively related to methylation level at NR1D1." (PMID 36447599, 2022). "We found that methylation level at NR1D1, but not CLDN22, remained related to infection status and that juvenile recruitment probability was positively related to methylation level at NR1D1." (PMID 36447599, 2022). "We found that methylation proportion at NR1D1, but not at CLDN22, remained related to infection status, which underscores the importance of performing follow‐up studies on candidate genes." (PMID 36447599, 2022). "We found that methylation proportion at NR1D1, but not at CLDN22 remained related to infection status, and that recruitment probability of fledged juveniles infected by S. trachea was positively related to methylation levels at NR1D1." (PMID 36447599, 2022).
cardiovascular diseases (3 papers, 2022 to 2023). "NR1D1 ameliorates thrombosis-based cardiovascular disorders associated with day/night cycles in animal models." (PMID 38072952, 2023). "Previous studies have shown that the decrease of Nr1d1 and Nr1d2 leads to dysfunction of circadian rhythm and aggravates cardiovascular diseases." (PMID 37018396, 2023).
adenocarcinoma (1 paper, 2025). A common cancer characterized by the presence of malignant glandular cells. "NR1D1 CRISPR KO significantly sensitized adenocarcinoma cells to ARSI ENZ with IC50 reduced from 30 μM to approximately 5 μM." (PMID 41231955, 2025). "Significantly, NR1D1 is elevated in NEPC tumors when compared with adenocarcinoma." (PMID 41231955, 2025). "Further examination revealed that ENZ treatment induced the expression of NR1D1/REV-ERBα and LP drivers, such as BRN2, ASCL1, FOXA2, and ONECUT2, in a dose and time-dependent manner in adenocarcinoma cells, with REV-ERBα being the fastest and strongest induced among them." (PMID 41231955, 2025).
colorectal (1 paper, 2021). "In our study cohort, we found a significant underexpression of PER1/2/3, CRY1/2 and NR1D1 proteins in CRC versus normal tissue, indicating an important role of these genes in colorectal carcinogenesis." (PMID 34440171, 2021).
myopathies (1 paper, 2022). "Our findings demonstrate that NR1D1 regulates muscle SR calcium homeostasis, pointing to its therapeutic potential for mitigating myopathy." (PMID 35917173, 2022). "Although out of scope of this study, these cellular processes may also contribute to the improvement of the myopathy phenotype upon NR1D1 activation." (PMID 35917173, 2022). "We have demonstrated that NR1D1 is expressed in DMD cells, albeit to a lower extent compared with control human myotubes, suggesting that increasing NR1D1 activity could represent a new therapeutic option in myopathies." (PMID 35917173, 2022). "Overall, we believe that our results identify NR1D1 as a new regulator of SR calcium homeostasis that may represent a therapeutic target in skeletal muscle disorders related to impaired reticular calcium homeostasis, such as myopathies." (PMID 35917173, 2022). "We also report that NR1D1 pharmacological activation by synthetic ligands may reveal therapeutic interests, because it improved calcium homeostasis in cells from patients with DMD and alleviated the myopathy phenotype in mdx/Utr+/– mice." (PMID 35917173, 2022).
neurodevelopmental disorder (1 paper, 2017). A behavioral and cognitive disorder with onset during the developmental period that involves impaired or aberrant development of intellectual, motor, or social functions. "Collectively, functional defects of NR1D1 as well as Oligophrenin-1 are likely to relate to the pathophysiology of neurodevelopmental disorders such as ASD and ID." (PMID 28262759, 2017). "The present study suggests that functional defects of NR1D1 may be implicated in the etiology and pathophysiology of ASD and other neurodevelopmental disorders, although further genetic and cell biological analyses are required to fully address the issue." (PMID 28262759, 2017).
NR1D1 also shares sentences with these, for which no sentence is quoted: Alzheimer disease (7 papers); heart failure (7); amyloid (4); inflammation (4); neurodegenerative disease (4); steatosis (4); ulcerative colitis (4); epilepsy (3); Sepsis (3); skin aging (3); Autoimmunity (2); cardiac hypertrophy (2); chronic obstructive pulmonary disease (2); cognitive deficits (2); dilated cardiomyopathy (2); Hepatitis (2); Hodgkins lymphoma (2); injury (2); lymphoma (2); melanoma (2); migraine (2); neurological diseases (2); non-alcoholic steatohepatitis (2); Parkinson disease (2); respiratory diseases (2); Abdominal obesity (1); acute myocardial infarction (1); adrenal hypoplasia congenita (1); airway hyperresponsiveness (1); alcohol use disorders (1).
A further 63 diseases each share a sentence with NR1D1 in 1 paper.